CA9 (carbonic anhydrase 9)
Diseases named in the same sentence as CA9 in open-access papers (continued):
Sharing a sentence is not in itself a finding about the gene and the disease.
non-small cell lung carcinoma (18 papers, 2008 to 2025). A group of at least three distinct histological types of lung cancer, including non-small cell squamous cell carcinoma, adenocarcinoma, and large cell carcinoma. "In non-small cell lung cancer, the CA9 up-regulation occurs in highly hypoxic/necrotic regions of the tumors and CA9 expression is strongly associated with poor outcome through the mechanism of angiogenesis, apoptosis inhibition, and cell-cell adhesion disruption." (PMID 24349364, 2013). "Our results are in line with increased CA9 FL expression shown in non-small cell lung cancer samples." (PMID 21910893, 2011). "In non-small-cell lung cancer, increased expression of CA9 mRNA in cancer tissues was significantly correlated with increased expression of the protein." (PMID 18841153, 2008). "A series of 98 tissue samples of primary non-small-cell lung carcinomas (NSCLC) from patients treated with surgery were analysed for the expression of CA9 and programmed-death ligand PD-L1 by cancer cells, and of FOXP3 by tumour-infiltrating lymphocytes (TILs)." (PMID 32066909, 2020).
squamous cell carcinoma (18 papers, 2004 to 2025). A carcinoma arising from squamous epithelial cells. "We intended to analyze the association of high CA9 expression with clinicopathologic features in the esophageal adenocarcinoma and squamous cell carcinoma groups." (PMID 26156831, 2015). "We analyzed the effect of high CA9 expression on overall survival in patients with esophageal adenocarcinoma or squamous cell carcinoma." (PMID 26156831, 2015). "However, there was a discrepancy in their results; the squamous cell carcinoma tissues seemed to have high CA9 expression, but this intensity of CA9 high expression in their figure was lower than that of the positive control (columnar cell metaplasia)." (PMID 26156831, 2015). "CA9 could be a unique marker to differentiate adenocarcinoma and squamous cell carcinoma in poorly differentiated esophageal cancer." (PMID 26156831, 2015). "The rate of high CA9 expression in patients with squamous cell carcinoma or squamous epithelium was significantly lower than that in patients with esophageal adenocarcinoma, high-grade dysplasia, low-grade dysplasia, Barrett esophagus, or columnar cell metaplasia." (PMID 26156831, 2015). "However, high CA9 expression was significantly more frequent in glandular lesions than in squamous epithelium (0 %) and squamous cell carcinoma (9 %)." (PMID 26156831, 2015). "Because only 1 patient with squamous cell carcinoma had high CA9 expression (1/23), we could not evaluate the association of CA9 expression with clinicopathologic characteristics for the squamous cell carcinoma group." (PMID 26156831, 2015). "However, we could not obtain mean or median survival duration for patients with high CA9 expression in the squamous cell carcinoma group since only 1 of these patients showed high CA9 expression." (PMID 26156831, 2015). "CA9 high expression occurred more frequently in glandular mucosa with or without dysplasia than in squamous epithelium or squamous cell carcinoma." (PMID 26156831, 2015). "High CA9 expression occurred predominantly in columnar cell lesions but was rare or absent in squamous cell carcinoma and squamous epithelium." (PMID 26156831, 2015). "In contrast, the very low frequency of high expression of CA9 in normal squamous epithelium and squamous cell carcinoma may be attributable to these tissues’ non-involvement by acid reflux." (PMID 26156831, 2015). "With our standard, the squamous cell carcinoma samples had low or no CA9 expression." (PMID 26156831, 2015). "Our findings show that patients with squamous cell carcinoma had low or no CA9 expression." (PMID 26156831, 2015).
ovarian carcinoma (17 papers, 2011 to 2024). A malignant neoplasm originating from the surface ovarian epithelium. "The presence of hypoxia, measured by tumour expression of HIF-1α or surrogate markers of hypoxia such as glucose transporter (GLUT)-1 or carbonic anhydrase 9 (CA9), has been shown to be associated with poorer survival in ovarian cancer patients." (PMID 26205780, 2015). "In order to identify the expression levels of several cancer-related genes in the pathogenesis of primary ovarian cancer, the present study examined the mRNA levels of hMOF, CA9, VEGF, HIF1α and hSTC1 in 47 patients with pathologically-diagnosed ovarian cancer using PCR." (PMID 24137335, 2013).
brain tumors (15 papers, 2008 to 2025). "Clinically, CA9 is minimally expressed in normal brain tissue, whereas its high expression in brain tumors strongly correlated with the level of malignancy." (PMID 31414377, 2019).
neuroblastoma (15 papers, 2011 to 2025). Neuroblastoma (NB) is the most common solid, extracranial childhood tumor. "Intriguingly, ZNF674-AS1 levels were positively correlated with increased CA9 mRNA levels both in publicly available neuroblastoma tissues and in our own sequencing data." (PMID 38177154, 2024). "In finding a novel ZNF674-AS1-CA9 axis, we assessed the clinical relevance between ZNF674-AS1 and CA9 in human neuroblastoma tissues." (PMID 38177154, 2024). "However, the association between CA9 and chemotherapy drug sensitivity in neuroblastoma has not been elucidated." (PMID 38177154, 2024). "Using several neuroblastoma cell lines in vitro, we showed that JQ1 inhibited hypoxia-dependent induction of HIF-1α and decreased the expression of the well-known HIF-1α downstream target gene CA9." (PMID 36139358, 2022). "As a contrast to RCC, we tested cancer transcriptome identification on single cell transcriptomes from neuroblastomas, which have no definitive single marker equivalent to CA9 in RCC." (PMID 36071103, 2022).
malignant mesothelioma (14 papers, 2019 to 2025). A malignant neoplasm of the pleura or peritoneum, arising from mesothelial cells. "In malignant mesothelioma (MM) cells, the overexpression of carbonic anhydrase 9 (CA-9) orchestrates iron metabolism, granting these cells a marked resistance to ferroptosis during hypoxic conditions." (PMID 38217037, 2024). "CA9 plays a role in equilibrating among hypoxia, iron metabolism and redox regulation in Malignant mesothelioma cells." (PMID 36702843, 2023). "A recent study reported that CA9 was involved in malignant mesothelioma resistance to ferroptosis under hypoxia." (PMID 36760347, 2023). "Hypoxia-mediated upregulation of CA9 expression and increased catalytic iron (Fe2+) has also been observed in malignant mesothelioma." (PMID 38099193, 2023). "In line with previous observations, high expression of the HIF-1 target gene carbonic anhydrase 9 had protective effects against ferroptosis in a model of malignant mesothelioma." (PMID 35906211, 2022). "al. demonstrated that carbonic anhydrase 9 (CA9) conferred resistance to ferroptosis in malignant mesothelioma under hypoxia." (PMID 34609072, 2021). "Inhibition of CA9 could decrease the viability and migration of malignant mesothelioma cells, while Fe2+ is increased via upregulating transferrin receptor and downregulating ferritin." (PMID 36230613, 2022). "Carbonic anhydrase 9 (CA9) confers resistance to ferroptosis/apoptosis in malignant mesothelioma cells, and inhibition of CA9 promotes mitochondrial fission and autophagy with increased levels of catalytic Fe2+, peroxides, mitochondrial O2−, and lipid peroxidation." (PMID 34485112, 2021). "Indeed, it must be noted that Carbonic anhydrase 9 (CAIX) has recently been shown to confer resistance to ferroptosis/apoptosis in malignant mesothelioma under hypoxia." (PMID 31828040, 2019). "Moreover, CA9 confers resistance to ferroptosis in malignant mesothelioma under hypoxia." (PMID 34878732, 2022). "In malignant mesothelioma under 1% O2 hypoxia, HIF-1 induces Carbonic anhydrase 9 (CA9) expression, which in turn reduces catalytic Fe2+ by downregulating TFRC and upregulating FTL and FTH1 to inhibit erastin-induced ferroptosis." (PMID 37048123, 2023).
oral cancer (14 papers, 2012 to 2022). "Our previous studies of oral carcinoma suggested that the CA9 polymorphism at rs2071676 was correlated with lymph node metastasis." (PMID 28667334, 2017). "The current study investigated relationships between SNPs (rs2071676, rs3829078, and 376del393) in the exon and 3′-UTR (rs1048638) regions of the CA9 gene and the risk of oral cancer." (PMID 23226559, 2012). "The synergistic effect of environmental factor (betel quid and smoking) and CA9 gene polymorphisms on the risk of oral cancer are well demonstrated." (PMID 23226559, 2012). "Moreover, a higher susceptibility to oral cancer was also found in patients with several CA9 SNPs and environment risk factors of betel chewing or tobacco consumption." (PMID 32365566, 2020). "It is also reported that CA9 gene polymorphisms, smoking and betel-quid chewing might alter oral cancer susceptibility and metastasis." (PMID 24349364, 2013). "In conclusion, our results suggest that gene-environment interactions between CA9 polymorphisms and betel-quid chewing with smoking may alter the susceptibility to oral-cancer development." (PMID 23226559, 2012). "Gene-environment interactions of CA9 polymorphisms, smoking, and betel-quid chewing might alter oral cancer susceptibility and metastasis." (PMID 23226559, 2012). "They investigated the CA9 mRNA level using datasets from The Cancer Genome Atlas (TCGA) of patients with oral cancer." (PMID 30654595, 2019). "Similar to our study, our previous studies showed that genetic polymorphisms of an oncogene (e.g., CA-9) or tumor suppressor gene alone (e.g., RECK) were unable to predict the risk of oral cancer." (PMID 25806809, 2015). "Previous study showed that SNP in the exon region of CA9 are associated with overall survival for metastatic renal cell carcinoma and gene-environment interactions of CA9 polymorphisms, smoking, and betel quid chewing might alter oral cancer susceptibility and metastasis." (PMID 24349364, 2013). "Distribution frequency of the clinical status and CA9 rs2071676 genotype frequencies in 462 patients with oral cancer." (PMID 23226559, 2012). "This caspase 3 activation appeared in the MECI-treated oral cancer cells (Ca9-22 and CAL 27)." (PMID 36139851, 2022). "Four single-nucleotide polymorphisms (SNPs) of the CA9 gene from 462 patients with oral cancer and 519 non-cancer controls were analyzed by a real-time polymerase chain reaction (PCR)." (PMID 23226559, 2012). "In our study, CA9 gene SNPs (rs2071676, rs3829078, rs1048638, and 376del393) alone did not contribute to oral-cancer susceptibility." (PMID 23226559, 2012). "Moreover, people who were either polymorphic for CA9 in 4 loci (+201, +1081, +1584, and +376) or who smoked were at a 4.13∼22.71-fold risk (p<0.001) of developing oral cancer, compared to people with the WT gene who did not smoke." (PMID 23226559, 2012). "Among 444 betel-nut consumers in our cohort, tobacco smoking significantly elevated the oral cancer risk in participants polymorphic for the rs2071676, rs1048638, and 376del393 polymorphisms of CA9, compared to people with the WT gene who did not smoke cigarettes." (PMID 23226559, 2012).
rectal cancer (14 papers, 2006 to 2026). A primary or metastatic malignant neoplasm that affects the rectum. "Further validation via dysadherin knockdown (KD) using the most effective siRNA sequence (#3) confirmed CA9 downregulation in SNU-254 cells (rectal cancer) and patient-derived primary cells." (PMID 41535258, 2026). "CA9 is a known prognostic marker for many cancers, such as ovarian cancer, esophageal and gastric adenocarcinomas, breast cancer and rectal cancer, as well as ICC." (PMID 30849962, 2019). "The strong staining intensity of CA9 is an adverse prognostic factor in rectal cancer." (PMID 35440019, 2022). "Tumour expression of thymidylate synthase, thymidine phosphorylase, cyclin A, vascular endothelial growth factor (VEGF), carbonic anhydrase-9, hypoxia inducible factor-1α, and glucose transporter-1 (GLUT-1) proteins was determined before and after rectal cancer surgery." (PMID 17016487, 2006).
metastatic disease (13 papers, 2011 to 2025). "Furthermore, metastatic tumors were found in the pancreas and mesentery of mice injected with control cells, but loss of CA9 led to a significant decrease in metastatic dissemination (p < 0.05 and <0.01, respectively)." (PMID 28667334, 2017). "Here, we use a single RCC243 cell line harboring a VHL mutation that was established by selecting for a carbonic anhydrase IX (CA9) marker of ccRCC from the primary tumor of a ccRCC patient who was diagnosed with metastatic disease." (PMID 40241258, 2025). "We found that the expression profile of the prognostic marker genes: CA9, VEGFA, and FN1, observed in in vivo orthotopic and metastatic tumor datasets was similar to the patient tumor datasets, whereas FN1 was only upregulated in the in vitro cell culture dataset." (PMID 40241258, 2025).
lung adenocarcinoma (12 papers, 2010 to 2023). A carcinoma that arises from the lung and is characterized by the presence of malignant glandular epithelial cells. "In conclusion, the appearance of CA9 SNP rs2071676 is negatively associated with the rate of EGFR L858R expression in the male population of lung adenocarcinoma." (PMID 32365566, 2020). "In the current study, the prevalence of CA9 SNP rs2071676 AG and AG + GG was significantly lower in male patients with lung adenocarcinoma and the EGFR mutation of L858R expression." (PMID 32365566, 2020). "Nevertheless, there are very few studies that have evaluated the association between CA9 SNP and the course of lung adenocarcinoma." (PMID 32365566, 2020). "We analyzed the relationship between CA9 mRNA expression level and tumor stage or histological grade in 305 lung adenocarcinoma patient samples." (PMID 36760347, 2023). "We further confirmed that the upregulated gene CA9 was related to poor prognosis in 76 EGFR-mutant lung adenocarcinoma patients (the testing set) from the TCGA database." (PMID 36760347, 2023). "The CyTOF showed the ITH of human primary lung adenocarcinoma for 14 markers; particularly, the higher expressions of GLUT1, MCT4, CA9, TMEM45A, and CD66 were associated with the lung-tumor tissue." (PMID 35008313, 2021). "Furthermore, the CA9 SNP rs2071676 is significantly correlated to both a lower tumor stage and lower risk for developing lymph node metastasis, whereas in the whole population of the male subgroup of lung adenocarcinoma, these results are mainly accompanied with the EGFR wild type." (PMID 32365566, 2020). "In the whole study population, the presence of CA9 SNP rs2071676 AG + GG were significantly correlated with a lower tumor stage of lung adenocarcinoma in both the whole study population (p = 0.044) and the EGFR wild type individuals (p = 0.033)." (PMID 32365566, 2020). "In the subgroup analysis of the male population, the presence of CA9 SNP rs2071676 AG + GG was also correlated with an earlier tumor stage (p = 0.037) and less possibility of lymph node invasion (p = 0.003) of lung adenocarcinoma in those with EGFR wild type." (PMID 32365566, 2020). "The current study explored the effect of CA9 gene polymorphisms and the epidermal growth factor receptor (EGFR) mutations on the clinicopathological characters of lung adenocarcinoma." (PMID 32365566, 2020). "The results of the current study may indicate that CA9 SNP rs2071676 could be used as a predictor of slow progression of lung adenocarcinoma." (PMID 32365566, 2020). "In addition, the CA9 SNP rs2071676 AG + GG genotype were significantly correlated to the lower tumor stage of lung adenocarcinoma in the whole study population (p = 0.044) and EGFR wild type individuals (p = 0.033)." (PMID 32365566, 2020). "In addition, the potential effects of different forms of CA9 SNP and EGFR mutations on the severity of lung adenocarcinoma were also evaluated." (PMID 32365566, 2020). "However, the percentage of early tumor stage was still numerically higher in lung adenocarcinoma males with CA9 SNP rs2071676, which might imply the CA9 SNP rs2071676 has a universal effect on the retardation of tumor progression." (PMID 32365566, 2020). "Herein, we aim to investigate the correlation between certain CA9 SNPs and EGFR variation in patients with lung adenocarcinoma." (PMID 32365566, 2020). "We further analyzed the potential correlation between the clinicopathologic characteristics of lung adenocarcinoma and the distribution of EGFR phenotype and CA9 SNP rs2071676." (PMID 32365566, 2020). "Further large cohort studies investigating the effect of CA9 SNP and EGFR phenotypes on the long-term survival rate of lung adenocarcinoma is mandatory." (PMID 32365566, 2020). "The tumor T-status, rate of distant metastasis and the distribution of cell differentiation of lung adenocarcinoma did not alter in different EGFR presentation with CA9 SNP rs2071676 (all p > 0.05)." (PMID 32365566, 2020).
lung adenocarcinoma (continued). "Consequently, the distribution of CA9 SNP and EGFR phenotypes is possible and may have a certain effect on the progression of lung adenocarcinoma, which is supported by the results of the current study." (PMID 32365566, 2020). "Moreover, since EGFR mutations are associated to other types of genetic polymorphism, some correlations between CA9 SNP and EGFR mutations that affect the presentation of lung adenocarcinoma may exist; so far, such research is absent." (PMID 32365566, 2020).
oral squamous cell carcinoma (12 papers, 2012 to 2025). "It has been reported that high CA9 expression is associated with reduced overall survival in oral cavity squamous cell carcinoma and poor pathological T-stage." (PMID 38016355, 2024). "In oral squamous cell carcinoma, a high CA9 mRNA level was associated with an increased risk of locoregional recurrence, while the expression level of CA9 was related to tumour grade and clinical stages in TSCC patients." (PMID 32299152, 2020). "The current study explored the combined effect of CA9 gene polymorphisms and exposure to environmental carcinogens on the susceptibility of developing oral squamous cell carcinoma (OSCC) and the clinicopathological characteristics of the tumors." (PMID 23226559, 2012). "Eckert et al8 demonstrated that CA9 levels in oral squamous cell carcinoma (OSCC) samples were higher than those in precancerous tissues." (PMID 32299152, 2020). "Here we show a comparative study that examines the prognostic value of CA9 mRNA, CAIX protein of tumor cells and secreted CAIX protein for oral squamous cell carcinoma (OSCC) patients." (PMID 30654595, 2019). "Recent evidence confirmed that CA9 was able to mediate the survival of oral squamous cell carcinoma patients and could be an independent prognostic factor." (PMID 32299152, 2020).
pancreatic ductal adenocarcinoma (12 papers, 2016 to 2024). An infiltrating adenocarcinoma that arises from the epithelial cells of the pancreas. "We also evaluated a possible relationship between CA9 expression and expression of immunity-related genes which were significantly upregulated in pancreatic ductal adenocarcinoma patients with a good prognosis compared to patients with a worse prognosis." (PMID 32707920, 2020). "In pancreatic ductal adenocarcinoma, CA9 expression was significantly lower in cases with well‐differentiated adenocarcinoma." (PMID 32299152, 2020). "A previous study showed that pancreatic ductal adenocarcinoma (PDACs) cells that express an activated KRAS increase the expression of CA9, via stabilization of hypoxia-inducible factor 1 subunit alpha (HIF1A) and HIF2A, which eventually regulates the pH and glycolysis." (PMID 33456371, 2020). "Upon hypoxic conditions, pancreatic ductal adenocarcinoma cells exhibited elevated HIF1A and HIF2A expression levels, increased expression of carbonic anhydrase 9, and activated glycolysis." (PMID 36925652, 2023).